DDC (dopa decarboxylase)
Description:
Catalyzes the decarboxylation of L-3,4-dihydroxyphenylalanine (DOPA) to dopamine and L-5-hydroxytryptophan to serotonin.
Synonyms: AADC
Tractability: Small molecule: an approved drug acts on it; a structure with a bound ligand is known; it has a high-quality binding pocket; it belongs to a druggable protein family.
Target class: Enzyme; Lyase
Safety:
Unwanted effects reported when the protein is acted on. In parentheses: how it was acted on, where the effect was seen, and who reports it.
addiction (source: ClinPGx)
Gene: Protein-coding gene on chromosome 7 (50,458,436 to 50,565,468, reverse strand). Ensembl gene ENSG00000132437.
Subcellular location (Human Protein Atlas): Actin filaments; Primary cilium
Pathways (Reactome):
Metabolism: Catecholamine biosynthesis; Serotonin and melatonin biosynthesis
Gene Ontology:
Molecular function: 5-hydroxy-L-tryptophan decarboxylase activity; aromatic-L-amino-acid decarboxylase activity; enzyme binding; L-dopa decarboxylase activity; protein binding; carbon-carbon lyase activity; carboxy-lyase activity; pyridoxal phosphate binding
Biological process: dopamine biosynthetic process; catecholamine metabolic process; serotonin biosynthetic process; amino acid metabolic process; biogenic amine biosynthetic process
Cellular component: extracellular exosome; cytosol; cytoplasm
Genetic constraint (gnomAD): Loss-of-function variants: 39 observed, 55.28 expected, observed/expected ratio (o/e) 0.71, 90% interval 0.55 to 0.92. The upper end of that interval is the gene's LOEUF score, 0.92, which puts it in group 3 of 6, group 1 being the genes least tolerant of losing a copy. Missense variants: 562 observed, 637.03 expected, observed/expected ratio (o/e) 0.88, 90% interval 0.82 to 0.95. Synonymous variants: 232 observed, 245.39 expected, observed/expected ratio (o/e) 0.95, 90% interval 0.85 to 1.05.
Gene-disease validity (ClinGen):
ClinGen rates the evidence that DDC causes each of these diseases.
aromatic L-amino acid decarboxylase deficiency (autosomal recessive): Definitive. Aromatic L-amino acid decarboxylase deficiency is a very rare, severe, genetic neurometabolic disorder associated with clinical manifestations related to underproduction of serotonin and dopamine, mainly hypotonia, hypokinesia, ptosis oculogyric crises, and signs of autonomic dysfunction.
Homologues: Orthologues: chimpanzee DDC (98% identical), macaque DDC (97% identical), mouse Ddc (89% identical), rabbit DDC (89% identical), rat Ddc (88% identical), pig DDC (88% identical), dog DDC (87% identical), guinea pig DDC (87% identical), tropical clawed frog ddc (74% identical), zebrafish ddc (71% identical), Drosophila melanogaster Ddc (60% identical), Caenorhabditis elegans bas-1 (43% identical), and 1 more. Paralogues in human: HDC (51% identical), GAD2 (23% identical), GAD1 (22% identical), CSAD (21% identical), GADL1 (21% identical), PDXDC1 (19% identical), SGPL1 (12% identical).
Diseases named in the same sentence as DDC in open-access papers:
DDC is named in the same sentence as 147 diseases in open-access papers, as found by Europe PMC text mining. Sharing a sentence is not in itself a finding about the gene and the disease. The quoted sentences say what the papers report.
Parkinson disease (52 papers, 2011 to 2025). A progressive degenerative disorder of the central nervous system characterized by loss of dopamine producing neurons in the substantia nigra and the presence of Lewy bodies in the substantia nigra and locus coeruleus. "In the early stages of Parkinson's disease (PD), levodopa (L‐dopa)/dopa decarboxylase inhibitor (DDCI) therapy is usually associated with significant improvements in motor disability." (PMID 38594812, 2024). "Both MPE and L-dopa improved parkinsonism but led to dose-dependent drug-induced dyskinesia (DID) when combined with dopa-decarboxylase inhibitor (DDCI) and benserazide (BZ)." (PMID 39392484, 2025). "Levodopa (L-DOPA) treatment, combined with the administration of dopa-decarboxylase inhibitors (DDCIs), is still the most effective symptomatic treatment of Parkinson’s disease (PD)." (PMID 37298741, 2023). "For instance, injecting the DNA of the aromatic amino acid decarboxylase (AADC, Dopa decarboxylase) in the striatum of patients with Parkinson’s disease to increase the conversion of L-Dopa into Dopamine." (PMID 36430666, 2022). "Benserazide hydrochloride is an aromatic l-amino acid decarboxylase (DOPA decarboxylase inhibitor) used with levodopa for the treatment of Parkinson’s disease." (PMID 34071060, 2021). "β-Asarone (M16; DL=0.06, BBB=1.24, and OB=35.61) increased striatal level of dopamine by enhancing dopa decarboxylase activity which improved behavioral competence in Parkinson's rat model." (PMID 30050590, 2018). "Despite several decades of active research into novel therapeutic strategies for PD, L-Dopa given in combination with a peripheral dopa-decarboxylase inhibitor, still remains the most powerful drug to alleviate the motor symptoms of Parkinson’s disease." (PMID 26322641, 2015). "Stalevo is an anti-parkinsonian dopaminergic combination medication that contains carbidopa, levodopa, and entacapone for the treatment of Parkinson's disease.Carbidopa inhibits aromatic-L-amino-acid decarboxylase (DOPA Decarboxylase or DDC)." (PMID 25411230, 2014). "Benserazide, an FDA‐approved Pkm2 inhibitor that inhibits peripheral dopa decarboxylase for the treatment of Parkinson's disease, has a weak effect on the induction of apoptosis; however, our results show that benserazide is still involved in combination therapy with Raf1." (PMID 39073026, 2024). "Based on the prominent roles of MAO, DDC, GSK-3 and PKA in the dopaminergic signaling involved in the beneficial role of resveratrol in parkinsonism as suggested in this study, their interactions with resveratrol were clarified using molecular docking." (PMID 40404673, 2025). "Dopa decarboxylase (DDC) is an important metabolic enzyme in Trp metabolism, which serves as an emerging biomarker for Parkinson’s disease in cerebrospinal fluid." (PMID 38974042, 2024). "In the second study, 782 patients with early Parkinson's disease were randomly allocated to approved treatments (levodopa and DOPA decarboxylase inhibitor alone; levodopa, DOPA decarboxylase inhibitor, and selegiline; or bromocriptine)." (PMID 31981516, 2020). "LA, whether combined with LD or not, elicited a significant response in α‐synuclein/dopa decarboxylase genetically modified Drosophila melanogaster Parkinsonism models." (PMID 39245995, 2024).
AADC deficiency (25 papers, 2013 to 2025). "In this study, we obtained a DDC‐KO model that recapitulates some key features of AADC deficiency in terms of enzyme activity loss and modifications of the l‐dopa/dopamine metabolic profile." (PMID 40318155, 2025). "Aromatic l-amino acid decarboxylase (AADC) deficiency (AADCd) is a rare autosomal recessive neurometabolic disease caused by pathogenic variants in the dopa decarboxylase (DDC) gene, located at the short arm of chromosome 7, encoding the AADC enzyme." (PMID 39280026, 2024). "Aromatic L-amino acid decarboxylase deficiency (AADCd) is a rare autosomal recessive neurometabolic disorder caused by AADC deficiency, an enzyme encoded by the DDC gene." (PMID 38275615, 2024). "Key diagnostic tests for AADC deficiency include the analysis of neurotransmitter metabolites in cerebrospinal fluid (CSF), measurement of AADC activity in plasma, and genetic testing to identify pathogenic variants in the DDC gene." (PMID 36928758, 2023). "First described in 1990, aromatic L-amino acid decarboxylase (AADC) deficiency is an ultrarare, autosomal recessive, neurotransmitter metabolic disorder resulting from pathogenic variants within the dopa decarboxylase (DDC) gene." (PMID 36928758, 2023). "AADC deficiency is a rare inherited neurologic disorder resulting from pathological variants in the dopa decarboxylase (DDC) gene encoding the AADC enzyme (EC 4.1.1.28)." (PMID 34551695, 2022). "Following the diagnosis of epilepsy with a presumed genetic etiology, we applied a diagnostic approach inclusive of a next-generation sequencing (NGS) gene panel, which uncovered two variants in trans in the DOPA decarboxylase (DDC) gene underlying an AADC deficiency." (PMID 38116105, 2023). "Such neurosurgical targeting has proven effective in aromatic L-amino acid decarboxylase (AADC) deficiency, where a recombinant AAV cassette containing a working copy of defective enzyme L-dopa decarboxylase is stereotactically injected into bilateral putamina or substantia nigra pars compacta." (PMID 34909266, 2021). "In patients with AADC deficiency (OMIM #608643), a global population of approximately 140 patients, mutations in the dopa decarboxylase (DDC) gene cause the profound loss of dopamine in the putamen." (PMID 34423296, 2021).
prostate carcinoma (7 papers, 2007 to 2024). A carcinoma that arises from epithelial cells of the prostate gland. "As reported, the DOPA decarboxylase (DDC) inhibitor carbidopa has exhibited anti-prostate cancer activity in vitro and in vivo." (PMID 39339498, 2024). "Downregulation of PAH and AOC1 and upregulation of DDC, LIN01436, and ORM1 were associated with the development of prostate cancer." (PMID 36497304, 2022). "Nonetheless, increased protein expression of the NE enzyme, dopa decarboxylase (DDC; E.C. 4.1.1.28) correlates with castrate-resistant disease, further supporting a NE program associated with castrate-resistant prostate cancer." (PMID 24551133, 2014). "Our recent studies using tissue microarrays and dual immunofluoresence indicate that in prostate cancer, DDC is not only a neuroendocrine (NE) marker, but is also co-expressed with AR in a subset of NE tumor cells." (PMID 17553164, 2007). "Our laboratory has shown that DDC is a coactivator of AR and a neuroendocrine marker of prostate cancer that increases in expression during hormone-ablation therapy and after progression to AI." (PMID 17553164, 2007).
neuroblastoma (6 papers, 2002 to 2025). Neuroblastoma (NB) is the most common solid, extracranial childhood tumor. "The need for a model of AADC deficiency in a cell line of neuronal origin prompted us to develop a KO for the DDC gene in the neuroblastoma SH‐SY5Y cell line." (PMID 40318155, 2025). "MRD detection in BM samples evaluated by a set of five markers (CHRNA3, DDC, GAP43, PHOX2B, and TH) was associated with poor outcome in patients aged over 1 year with stage 4 neuroblastoma." (PMID 31214500, 2019). "When BM samples are evaluated by a set of five markers (CHRNA3, DDC, GAP43, PHOX2B, and TH), unfavorable outcome in localized neuroblastoma patients is associated with the detection of more than one positive-marker." (PMID 31214500, 2019). "Suppression of SRY in human neuroblastoma cell line, M17, results in a depressed expression of TH, DOPA decarboxylase (DDC), dopamine β-hydroxylase (DBH), and monoamine oxidase A (MAO A) expression." (PMID 29200993, 2017). "Therefore, in neuroblastoma, pyridoxal phosphate is utilised for dopa decarboxylase activity." (PMID 33603049, 2021). "The combined signature of five markers (CHGA, DCX, DDC, PHOX2B, and TH) expression in BM and PB was correlated with PFS of relapsed/refractory neuroblastoma." (PMID 31214500, 2019). "Dopa decarboxylase (DDC) is responsible for the synthesis of the key neurotransmitters dopamine and serotonin, and is frequently expressed in neuroblastoma and small cell carcinoma of the lung." (PMID 12402156, 2002). "Given the lack of a reliable model for the disease, we developed a dopa decarboxylase knockout model using CRISPR/Cas9 technology in the SH‐SY5Y neuroblastoma cell line." (PMID 40318155, 2025).
COVID-19 (5 papers, 2021 to 2023). A disease caused by infection with severe acute respiratory syndrome coronavirus 2. "In COVID-19, it has been postulated that modifications of the dopamine and serotonin synthetic pathways contribute to COVID-19 pathophysiology, as gene co-expression, co-regulation, and function are linked between Angiotensin I Converting Enzyme 2 (ACE2) and Dopa Decarboxylase (DDC)." (PMID 35552501, 2022). "Kenneth Blum’s study found that dopamine synthesis might decrease in COVID-19, because SARS-Cov2 would induce down-regulation of angiotensin I converting enzyme 2 (ACE2) gene expression and the coexpression gene of dopa decarboxylase." (PMID 36690957, 2023).
Dystonia (5 papers, 2015 to 2021). An abnormally increased muscular tone that causes fixed abnormal postures. "AADC (aromatic l-amino acid decarboxylase) deficiency (AADD) is caused by homozygous or compound heterozygous mutations in the DDC gene that result in combined serotonin and catecholamine deficiency, dystonia, and severe neurologic dysfunction." (PMID 33996898, 2021).
schizophrenia (5 papers, 2016 to 2025). A major psychotic disorder characterized by abnormalities in the perception or expression of reality. "According to this idea, in a PET study on nine schizophrenia patients, 5-week haloperidol therapy caused a significant decrease in DOPA decarboxylase relative activity in the caudate, the putamen, the thalamus, and the orbital and frontal cortices." (PMID 36979877, 2023). "DDC is an enzyme required for dopamine synthesis, and aberrant dopamine synthesis is hypothesized to underlie symptoms related to schizophrenia." (PMID 36980961, 2023). "Importantly, within each of these canonical pathways were genes either encoding proteins involved in rate limiting steps (e.g. glutamate decarboxylase and dopa decarboxylase) or transporters (GABA transporter) or receptors (GABAB) that have genetic associations as risk factors for schizophrenia." (PMID 27382048, 2016).
neuroendocrine tumors (4 papers, 2012 to 2023). "Notably, the expression of genes found to be typically active in neuroendocrine tumors (Hofsli gene signature) were also significantly diminished in 424GC cells, including genes encoding neuroendocrine markers such as chromogranin A, dopa decarboxylase (DDC) and TPH1." (PMID 22253802, 2012).
vitiligo (4 papers, 2004 to 2021). Generalized well circumscribed patches of leukoderma that are generally distributed over symmetric body locations and is due to autoimmune destruction of melanocytes. "The mRNA expression of DRD1 and DRD5, including GPX1, dopa decarboxylase (DDC), and monoamine oxidase A (MAOA), differs in vitiliginous skin, and the protein levels of DRD1, DRD5, DDC, MAOA, and MAOB vary in the skin and/or blood serum of patients with vitiligo." (PMID 34360837, 2021).
breast carcinoma (3 papers, 2016 to 2020). "Carbidopa is used for the treatment of Parkinson’s disease (PD) as an inhibitor of DOPA decarboxylase, and PD patients taking carbidopa have a lower incidence of various tumors, except for breast cancer and melanoma." (PMID 31450593, 2019). "To experimentally validate this prediction, we examined the effect of serotonin and carbidopa, an inhibitor of DOPA Decarboxylase, on breast cancer cell lines." (PMID 26813959, 2016).
depression (3 papers, 2016 to 2025). "Of thirteen depression‐associated DRPs, seven proteins including DDC, FGFR2, KIBRA, MED22, OLIG1, RAI1, SLIT2 were upregulated, whereas six proteins including COX3, CRHBP, CSMD1, FSTL1, GRIK4, and LMTK3 were downregulated." (PMID 39373701, 2024).
gastric cancer (3 papers, 2004 to 2022). A primary or metastatic malignant neoplasm involving the stomach. "We found that high expression of CPVL, ONECUT2, DDC, PRSS21, and GRTP1 increase the risk of gastric cancer." (PMID 35754804, 2022). "DDC is overexpressed in gastric cancer peritoneal dissemination, but the role of DDC in such dissemination is still unclear, so that further investigation is necessary to clarify it." (PMID 14760382, 2004). "The high risk-scores of CPVL, ONECUT2, DDC, PRSS21, and GRTP1 could be used to determine the degree of malignancy and prognosis in gastric cancer patients." (PMID 35754804, 2022). "To find out the role of hub genes in the overall survival of gastric cancer we performed a multivariate Cox regression analysis, among 21 hub genes, the eight genes (KCNJ3, CPVL, ONECUT2, SLC19A3, DDC, PRSS21, F12, and GRTP1) were designated as independent indicators of poor prognosis." (PMID 35754804, 2022). "Subsequently, NE synthetase enzymes tyrosine hydroxylase (TH), dopa decarboxylase (DDC), and dopamine-β-hydroxylase (DBH), degrading enzymes monoamine oxidase A and B (MAOA and MAOB), and catechol-O-methyl transferase (COMT) were analyzed in TCGA database of gastric cancer." (PMID 33855088, 2021).
Hypertension (3 papers, 2019 to 2024). The presence of chronic increased pressure in the systemic arterial system. "Methyldopate HCl is an inhibitor of the enzyme DOPA decarboxylase used in treatment of hypertension." (PMID 30631100, 2019).
pheochromocytoma (3 papers, 2019 to 2025). "Then, we constructed amino acid metabolism profiles by WGCNA and LASSO regression model for investigating the impact of amino acid metabolism on pheochromocytoma pathogenesis and immunity and identified six hub genes (DDC, SYT11, GCLM, PSMB7, TYRO3, and AGMAT)." (PMID 38526709, 2025).
viral infection (3 papers, 2019 to 2022). "This is because PI3K is dependent on the accumulation of DOPA decarboxylase, the enzyme involved in the production of dopamine, which is reduced by a viral infection." (PMID 34290708, 2021). "In the present study, we reveal that l-dopa decarboxylase (DDC), an enzyme that catalyzes the biosynthesis of dopamine, is a determinant factor of the Flaviviridae viruses DENV and HCV life cycle and, in turn, is negatively regulated by viral infection." (PMID 31387309, 2019).
colitis (2 papers, 2024 to 2026). Inflammation of the colon. "AS-IV ameliorated colitis by downregulating IDO1 expression, while upregulating the expression of tryptophan hydroxylase 1 (TPH1), DDC, monoamine oxidase A (MAO-A), and the aryl hydrocarbon receptor (AhR), as well as inhibiting NF-κB p65 phosphorylation." (PMID 42195848, 2026). "In vivo: 3.5% DSS-induced experimental colitis mice were treated with BTW (Pulsatilla chinensis (Bunge) Regel, Phellodendron chinense C. K. Schneid, Coptis chinensis Franch and Fraxinus chinensis Roxb), kynurenine or DOPA decarboxylase (DDC) inhibitor (carbidopa)." (PMID 38974042, 2024).
colorectal adenocarcinoma (2 papers, 2010 to 2012). The most common type of colorectal carcinoma. "Elevated DDC mRNA expression levels were found in well-differentiated and early-stage colorectal adenocarcinomas, and were shown to predict better patient outcome, in terms of DFS and OS." (PMID 23083099, 2012). "In this study, we investigated the expression of the DDC gene in colorectal adenocarcinoma and its prognostic significance." (PMID 20424616, 2010). "Moreover, DDC has a similar expression pattern in colorectal adenocarcinoma, possessing favorable prognostic value." (PMID 23083099, 2012).
Tremor (2 papers, 2021 to 2022). An unintentional, oscillating to-and-fro muscle movement about a joint axis.
atherosclerosis (1 paper, 2022). A disease characterized by the build-up of fatty material and calcium deposition in the arterial wall resulting in partial or complete occlusion of the arterial lumen. "Dopa decarboxylase (DDC), the enzyme that produces the neurotransmitter dopamine, was encapsulated separately from the fluorophore DY-633, resulting in clusters serving both imaging and therapeutic purposes (such as for the treatment of atherosclerosis)." (PMID 35628527, 2022).